RAD52 (RAD52 DNA repair protein)
Diseases named in the same sentence as RAD52 in open-access papers (continued):
Sharing a sentence is not in itself a finding about the gene and the disease.
cancer (continued). "Common synthetic lethality partnersare BRCA1/2, which play a vital role in annealing RAD51 to ssDNA;however mutations in these proteins are quite common, and when this occurs, the cancer cell can compensateby utilizing RAD52 to perform the task instead." (PMID 33135887, 2020). "Some tumours show a RAD52 addiction, thus giving the opportunity to kill cancer cells by RAD52 inhibition." (PMID 32098397, 2020). "Targeting RAD52 in BRCA-depleted cancer cells will sensitize them to the toxic effect of DSBs, while normal cells and tissues with intact BRCA1/2-dependent HR should not be influenced." (PMID 31615159, 2019). "Some studies have been reporting alterations in the expression patterns of RAD52 gene after exposition of cancer cells to DNA-damaging agents." (PMID 31652722, 2019). "A number of RAD52 inhibitor leads were reported and showed effects to selectively kill BRCA1- and BRCA2-deficient cancer cells." (PMID 31569559, 2019). "In human cancer cell-lines with defective function of BRCA1, PALB2 or BRCA2, RAD52′s depletion increases damage-associated chromosomal abnormalities, decreases clonal viability, and also reduces the HR activity." (PMID 31652722, 2019). "This makes it an attractive therapeutic target in cancer, as tumors with BRCA mutations would be susceptible to loss of RAD52, while normal tissues with an intact HR pathway should survive without it." (PMID 31340507, 2019). "Given that RAD52 is a non-essential gene for normal cells but is indispensable for tumor cells to survive, RAD52 presents as a good target for cancer treatment." (PMID 31569559, 2019). "Together, these results demonstrate the exciting therapeutic potential of targeting RAD52-mediated DNA repair, particularly in BRCA-deficient cancers." (PMID 29757235, 2018). "6-OH-dopa is reported to suppress RAD52 recruitment and recombination activity in vitro (by disrupting RAD52 heptamer and undecamer ring superstructures), selectively inhibiting the proliferation of BRCA deficient cancer cells." (PMID 29757235, 2018). "Oncogenic data surrounding RAD52 and the DNA damage response elucidate how DNA damage and repair remain at the cornerstone of cancer at every level, modulating the disease from initiation to progression and even throughout treatment." (PMID 28722656, 2017). "This study indicates that the mechanism of synthetic lethality in RAD52-depleted BRCA1 mutant cancer cells depends on the endonuclease EEPD1." (PMID 29145865, 2017). "Our novel observations suggest that knockout of the Rad52 gene in an in vivo mouse model of carcinogenesis decreases murine lung hyper-plasia, in situ carcinoma and lung SCC." (PMID 28722656, 2017). "Depletion of EEPD1 also reduced fork restart albeit to a lesser degree than RAD52 depletion in the BRCA1-/- cancer cells." (PMID 29145865, 2017). "Targeting Rad52 has been shown to eliminate cancer stem and progenitor cells, induce high levels of spon-taneous DNA damage and decrease tumorigenesis without detectable effects on normal cells and tissues." (PMID 28722656, 2017). "In a separate line of investigation, RAD52 was identified as essential for viability of cancer cells with defects in various HR proteins including BRCA1, BRCA2, and partner and localizer of BRCA2 (PALB2)." (PMID 29145865, 2017). "6-OH-dopa inhibited RAD52 foci formation in response to DNA damage in murine hematopoietic cells deficient in BRCA1 and selectively killed BRCA1 and BRCA2-deficient human cancer cells." (PMID 27649245, 2016). "Future studies that employ the small molecule drugs identified so far will also help to determine exactly how RAD52 works in human cells and how it helps cancer cells to survive." (PMID 27434671, 2016). "Further work is needed to demonstrate the efficacy of RAD52 inhibitors in killing BRCA1- and BRCA2-deficient cancer cells in vivo." (PMID 27649245, 2016).
cancer (continued). "In order to identify alternative promoters with high specificity to cancer cells we examined the tumor specificity of Rad51 paralogs Rad51B, Rad51C, Rad51D and Rad52." (PMID 24742710, 2014). "To identify cancer-specific promoters we first compared the expression levels of Rad51B, Rad51C, Rad51D and Rad52 in a panel of seven normal and seven cancerous cells lines." (PMID 24742710, 2014). "Here, we explored the utility of the HR gene Rad51B, Rad51C, Rad51D and Rad52 for transcriptionally targeted therapy of cancer." (PMID 24742710, 2014). "This identified many genes, including CylinD1/D3, Cdk1/2, Psme3, Rad52/54L and Skp2 that have previously been shown to be dysregulated in cancer." (PMID 23762407, 2013). "RAD52 plays important roles in DNA repair, cancer development, and antibody class switching." (PMID 39796194, 2025). "This could be one of the reasons why combined inhibition of Polθ with PARP1 or RAD52 kills cancer cells more effectively than inhibition of Polθ separately, while the effect of the treatment is less profound in normal cells." (PMID 39273083, 2024). "Inactivation of RAD52 in homologous-recombination-deficient BRCA1- or BRCA2-defective cells is synthetically lethal, and aberrant expression of RAD52 is associated with poor cancer prognosis." (PMID 38658755, 2024). "The synthetic lethal relationship between RAD52 and BRCA1/2 supports the notion that there may be therapeutic opportunities to specifically inhibit RAD52 in homologous-recombination-deficient cancer cells." (PMID 38658755, 2024). "On the other end, RAD52 overexpression was reported in many other cancer types, sustaining the speculation that RAD52 is important to enhance the viability of cancer cells and the dysregulation of cancer cells’ DNA repair mechanisms." (PMID 36980703, 2023). "This reliance on the error-prone RAD52 in BRCA1/2-deficient cells can result in genomic rearrangements and instability, significantly contributing to an elevated mutation burden and advancing cancer progression." (PMID 38136334, 2023). "RPA and RAD52 co-localized at the telomeres of ALT-positive cancer cells marked by telomere repeat binding factor 2 (TRF2), and their association with telomeres was further enhanced by replication stress or when ALT activity was increased by FANCM depletion, as has been demonstrated previously." (PMID 36894693, 2023). "It is interesting that depending on the different types of cancer, RAD52 was found to be up- or down-regulated, and RAD52 levels might correlate with a good or poor prognosis for the patients." (PMID 36980703, 2023). "Indeed, RAD52 has an important oncogenic role in mediating many DDR pathways on which cancer cells rely when canonical pathways are disrupted." (PMID 36980703, 2023). "Initially regarded as having a major role only in error-prone backup DNA repair mechanisms, RAD52 has recently gained attention because its inhibition induces synthetic lethality in cancer cells with an inactivated homologous recombination pathway (for error-free double-strand-break repair)." (PMID 36980703, 2023). "Therefore, even though all the evidence suggests that RAD52 is a promising pharmacological target for cancer therapies, researchers still have very limited knowledge about this multifaceted protein." (PMID 36980703, 2023). "It further suggests that while RAD52 inhibitors may prove effective in treating cancers with BRCA1 defects, resistance may arise if tumor cells suppress EEPD1 expression or otherwise inactivate EEPD1." (PMID 38069223, 2023). "MiDAS inhibition specifically by targeting RAD52 may serve as a therapeutic strategy in the elimination of cancer cells." (PMID 36253342, 2023). "Motivated by their previous evidence in budding yeast Rad52, they confirmed that curcumin inhibited RAD52 expression in human cancer cells too, using the MCF-7 cell line treated with the irinotecan (CPT-11) damaging agent and then with different curcumin conditions." (PMID 36980703, 2023).
cancer (continued). "Truncated C-terminus RAD52 alleles have been previously shown to suppress certain germline BRCA2 mutations and the E320* RAD52 truncation also co-occurs with BRCA2 mutations in human cancers." (PMID 36530474, 2022). "Several studies demonstrated that unlike normal cells, RAD52 is required for the survival of cancer cells with loss-of-function mutation in genes such as BRCA1, BRCA2, PALB2, and RAD51 paralogs." (PMID 35463312, 2022). "Not surprisingly, the pro-oncogenic role of RAD52 is especially pronounced in cancer cells that are deficient in DDR pathways, like ATM-deficient cancers." (PMID 34887904, 2021). "Our data suggest that strategies targeting XAB2 and/or RAD52 may help improve the therapeutic outcome of cancer patients treated with seDSBs-inducing DNA damaging agents." (PMID 34500463, 2021). "Therefore, Rad52 has potential as a therapeutic target in the treatment of these and some other cancers." (PMID 34887904, 2021). "RAD52 inactivation increased cell death in lung tumors and in BRCA2-deficient cancer cells." (PMID 34201502, 2021). "The results also suggest a potential of RAD52 inhibitors to treat a wide range of HR-deficient cancers with or without PARPi-resistance." (PMID 33784323, 2021). "Several studies have explored targeting RAD52 to attack cancer cells with some success." (PMID 33784323, 2021). "Several studies demonstrated that RAD52 is important for enhanced viability of cancer cells." (PMID 34887904, 2021). "Importantly, RAD52 promotes non-S-phase telomeric DNA synthesis specifically in ALT-positive cancer cell lines, and RAD52 deletion was shown to reduce telomere length in these cells." (PMID 32938550, 2021). "In this study, we have performed a virtual screening by targeting the self-association domain (residues 85–159) of RAD52 with a library of 66,608 compounds and found one compound, C791-0064, that specifically inhibited the proliferation of BRCA2-deficient cancer cells." (PMID 33995041, 2021). "Human RAD52 was recently revealed as a promising candidate for targeted therapy in relation to its important role in replication fork metabolism, promoting cellular viability in cancer cells." (PMID 34201502, 2021). "Unlike yeast rad52 null mutants, Rad52 knock-out mice show no or mild deficiency in DNA repair; they are viable, fertile, and do not display cancer predisposition." (PMID 33275133, 2020). "Contrary to BRCA2 that promotes Rad51-dependent recombination, gene amplifications rather than mutations have been observed for RAD52 in cancer cells." (PMID 32355220, 2020). "Indeed, in BRCA2-deficient cancer cells, unprotected regressed arms become the entry point for MRE11, whose recruitment is performed by RAD52, which binds MRE11." (PMID 32050645, 2020). "While biochemical features of RAD52, its more novel double-strand break (DSB) repair functions and its modifications are the focus of other reviews in this issue, here, we will discuss the unexpected roles that RAD52 plays at the DNA replication fork and their implications for cancer therapy." (PMID 32050645, 2020). "In addition, we discuss RAD52 inhibition in DDR-defective cancers as a possible target to improve cancer therapy efficacy." (PMID 31652722, 2019). "Recent studies demonstrated that RAD52 has an important role in genomic stability maintenance and cancer suppression in mammalian cells, while several HR proteins including BRCA1, BRCA2, PALB2, and RAD51 paralogs (RAD51B, C, D, and XRCC 2 and 3) present an inactivated and depleted activity." (PMID 31652722, 2019). "The RAD52 gatekeeper role at the perturbed replication forks, which we describe here, may be also relevant to several types of cancer." (PMID 30926821, 2019). "Since RAD52 plays an essential role in break-induced replication repair, this finding may explain the amplification of RAD52 in human cancers and why its inactivation disrupts cancer development." (PMID 31719794, 2019).
cancer (continued). "For example, overexpression of RAD52 may prevent excessive fork reversal making cancer cells differentially sensitive to some anticancer drugs." (PMID 30926821, 2019). "Since RAD52 is involved in protecting stalled replication forks and repairing collapsed forks, cancer cells may rely more on RAD52 than normal cells to survive due to oncogenic replication stress." (PMID 31569559, 2019). "Therefore, RAD52 has important recombination roles under special stress conditions in mammalian cells, and presents as a promising anti-cancer therapy target." (PMID 31569559, 2019). "This review highlights recent reports indicating that reducing homologous recombination through inhibition of RAD52 may represent an important focus for cancer therapy and the specific efforts that are already demonstrating potential." (PMID 28722656, 2017). "Thus, RAD52 has emerged as a target of interest for pharmaceutical intervention for novel synthetic lethal treatment strategies for BRCA1/2 mutant cancers." (PMID 29145865, 2017). "In concordance, inhibition of RAD52 DNA binding activity by small peptide aptamer exerted synthetic lethality in BRCA1 and BRCA2 mutated cancer cells and shRNA-mediated downregulation of RAD52 is lethal in tumor cell lines carrying BRCA2 inactivating mutations." (PMID 26784987, 2016). "Unlike yeast rad52 mutants which show strong deficiency in nearly all types of HR events including DSB repair, RAD52−/− mice are viable, show only moderate decrease in HR, no DNA damage sensitivity, fertile without abnormalities or cancer predisposition." (PMID 27649245, 2016). "Small molecules that block the interaction between the RAD52 protein and DNA might therefore help to kill cancer cells." (PMID 27434671, 2016). "In summary, RAD52 SNPs, either individually or collectively, may modify gene function and alter RAD52 protein expression levels, thus rendering cancer cell resistant to platinum agents." (PMID 23209746, 2012). "Our findings revealed an antagonistic interaction between cisplatin and high-THC cannabis extract, which could be linked to alterations in gene transcription associated with cell death (BCL2, BAD, caspase 10), DNA repair pathways (Rad52), and cancer pathways related to drug resistance." (PMID 38674023, 2024). "Also, its demonstrated that FANCD2 supports MiDAS in parallel with RAD52 in cancer cell lines." (PMID 36253342, 2023). "However, RAD52 has since been reevaluated as a potential target for cancer treatment." (PMID 36980703, 2023). "While RAD52 was initially considered to be a non-essential auxiliary factor, its inhibition has more recently been demonstrated to be synthetically lethal in cancer cells bearing mutations and inactivation of specific intracellular pathways, such as homologous recombination." (PMID 36980703, 2023). "Interestingly, all three compounds showed selective cytotoxicity to HCC1937, indicating the RPA:RAD52 PPI is an effective target for selective killing of BRCA-mutated cancer cell line regardless of the status of synthetic lethality with PARPi." (PMID 33784323, 2021). "Moreover, combination of RAD52 and PARP1 inhibitors could improve the response to treatment in HR-deficient cancers." (PMID 34201502, 2021). "Recent studies suggest that RAD52-driven BIR may promote genome instability in human cancers." (PMID 34887904, 2021). "Therefore, RAD52 can be targeted in synthetic lethality in these two groups of cancers." (PMID 33671579, 2021). "Therefore, “dual pathway synthetic lethality” simultaneously targeting PARP1 and RAD52 offers a promising and very aggressive therapeutic approach against HR-compromised tumors, allowing for more robust elimination of cancer cells and preventing the emergence of drug resistance." (PMID 31615159, 2019). "Finally the human RAD27 homolog FEN1 and RAD52, as well as many other genes involved in DNA replication, repair and recombination, can be over- or under-expressed in human cancers thus producing genetic instability." (PMID 31164905, 2019).
cancer (continued). "Finally, this study also showed that the therapeutic outcome may be improved by RAD52 inactivation of BRCA genes-defective cancers and treated with agents that inhibit PARP, while inducing a minimal toxicity to normal cells." (PMID 31652722, 2019). "Thus, targeting Rad52 could turn out to be a new way to therapeutically exploit vulnerabilities that occur selectively in cancer cells." (PMID 29548335, 2018). "We hope the concept proposed here may not only inspire further mechanistic studies, but also attempts to target Rad52 in cancer, as a way to selectively induce lethal chromosomal instability in Rad52-dependent cancers, while sparing normal tissues whose genome maintenance does not depend on Rad52." (PMID 29548335, 2018). "Finally, elucidation of the mechanisms underlying the synthetic lethality between RAD52 and BRCA1/224–26 could identify potentially attractive therapeutic approaches for cancers in which BRCA1/2 is mutated." (PMID 30250272, 2018). "Thus, EEPD1 could be used as a biomarker for treatments that target RAD52 in BRCA1/2 mutant cancers." (PMID 29145865, 2017). "Given that depleting EEPD1 prevents synthetic lethality of RAD52 repression in BRCA1 mutant cancer cells, potential mechanisms by which cancer cells could become resistant to clinically useful RAD52 inhibitors are by repressing EEPD1 expression or acquiring EEPD1 loss-of-function mutations." (PMID 29145865, 2017). "Thus, by targeting Rad52, the ensuing inhibition of cancer cell-related DNA repair may amplify both endogenous and drug-induced DNA damage, sensitizing tumor cells to cell death." (PMID 28722656, 2017). "However, the molecular mechanism by which RAD52 deficiency causes synthetic lethality of BRCA1/2 mutant cancer cells has not been identified." (PMID 29145865, 2017). "In addition to its obvious uses in cancer therapy, the RAD52-ssDNA binding inhibitors can be utilized as molecular probes to assist in distinguishing the cellular pathways that depend on the main biochemical activity of RAD52." (PMID 27434671, 2016). "In addition, one of the 9 active compounds, adenosine 5’-monophosphate (A5MP), and also its mimic 5-aminoimidazole-4-carboxamide ribonucleotide (AICAR) 5’ phosphate (ZMP) inhibited RAD52 activity in vivo and exerted synthetic lethality against BRCA1 and BRCA2–mutated carcinomas." (PMID 26784987, 2016). "The protein has emerged as a promising therapeutic target due to synthetic lethal interactions with BRCA1, SMARCAL1, and RAD52, and in ALT-positive cancers." (PMID 40447800, 2025). "Given that numerous RAD52 small molecule inhibitors have been described that may be translatable for use in the clinic, expanding the understanding of when cells become reliant on RAD52 will inform the successful application of such inhibitors in cancer treatment." (PMID 39561207, 2024). "It is shown that the nanomedicine platform can be applied for combinatorial therapy by incorporating the anti‐cancer drug olaparib and targeting the RAD52 gene, leading to significant anti‐tumor effects in BRCA‐mutant cancer." (PMID 37485817, 2023). "Since BRCA1 is important for initiating end resection in normal cells, BRCA1-mutant cancer cells use EEPD1 to cleave stressed replication forks and initiate end resection during RAD52-mediated HR repair of stressed replication forks." (PMID 36683914, 2023). "Currently there is an increasing clinical interest in the use of RAD52 inhibitors (in addition to inhibitors of PARP, Chk1, and Polθ) in order to exacerbate the RS in human cancers." (PMID 34201502, 2021). "Mitoxantrone and doxorubicin, are anti-cancer drugs in clinical use and displayed RPA:RAD52 PPI inhibition in FluorIA and had the highest cytotoxicity in BRCA-deficient cancer cell lines." (PMID 33784323, 2021). "Therefore, RAD52 may be targeted in synthetic lethality in cancer." (PMID 33671579, 2021). "However, how RAD52 activity helps HR-deficient cancers to survive is not clear." (PMID 33784323, 2021).